ATG7 (autophagy related 7)
Diseases named in the same sentence as ATG7 in open-access papers (continued):
Sharing a sentence is not in itself a finding about the gene and the disease.
lung carcinoma (continued). "Additionally, the long non-coding RNA NNT-AS1 regulates cisplatin resistance in lung cancer cells through the miR-1236-3p/ATG7 axis, indicating the critical role of ATG7-mediated autophagy in the biological functions and therapeutic resistance of malignant tumors." (PMID 39464718, 2024). "Through the genetically engineered mouse models, ATG7 ablation was found to block tumor growth and induce tumor cell death in lung cancer, indicating that autophagy inhibition might serve as a promising strategy for lung cancer therapy." (PMID 31337985, 2019). "Overall, in lung cancer cells treated with SM-3, there was a significant conversion of LC3B-I to LC3B-II, along with increased levels of ATG7, ATG5, and p62." (PMID 40287470, 2025). "The results indicated that the expression of ATG7 and ATG5 proteins was elevated in lung cancer cells treated with SM-3 compared to those treated with Res." (PMID 40287470, 2025). "Treatment of lung cancer cells with SM-3 resulted in autophagic cell death, as evidenced by the conversion of LC3I to LC3II, along with increased levels of ATG7, ATG5, and p62." (PMID 40287470, 2025). "In lung cancer, for NSCLC, METTL3 promotes autophagy by upregulating the expression of LC3B, ATG5, and ATG7, protecting drug-resistant cells from death and leading to the development of resistance to gefitinib." (PMID 39468015, 2024). "Gefitinib was shown to promote autophagy in lung cancer cell lines, as indicated by LC3II lysosomal localization, increased ATG5 and ATG7 expression at the mRNA or protein levels, and reduced phosphorylation of the PI3K/Akt/mTOR pathway." (PMID 39272847, 2024). "For example, in the lung cancer models of Cre–activatable KrasG12D or BrafV600E, the conditional KO of ATG5 or ATG7 accelerated tumor initiation which were, however, diverted to benign oncocytoma." (PMID 36187114, 2022). "In this way, enhanced ATG7 levels promote the conversion of LC3-I into LC3-II and improve Beclin-1 expression, supporting autophagy and chemoresistance of lung cancer (Huang FX." (PMID 35444536, 2022). "Here, we reported that juglanin increased LC3, ATG7, Beclin1 and PIK3C3 expression, contributing to autophagy formation accompanied with the exterior of acidic vesicular organelles in lung cancer cells." (PMID 29212196, 2017). "Future work will be required to address the molecular mechanism by which NASTRp suppresses autophagy or related molecules such as ATG7, ATG5 and p62 in lung cancers." (PMID 25897662, 2015). "In cisplatin-resistant human lung cancer cells, FTY720 combined with cisplatin enhanced the antitumor effect of cisplatin on cisplatin-resistant lung cancer cells by down-regulating the expression of Atg7." (PMID 41154714, 2025). "In another study, bis-indole derivatives of 1-methoxyspirobrassinol methyl ether induced autophagy in A549 (lung carcinoma epithelial cells) by modulation of the phosphorylation or expression of various autophagy markers, such as Beclin-1, AMPK, ULK1, p62, Atg7, and LC3A/B." (PMID 38675591, 2024). "In addition, using Kaplan-Meier analysis, we found that patients with high expression levels of ATG7, and especially those with LUAD, showed unfavorable survival in lung cancers." (PMID 36105209, 2022). "Interestingly, knocking-out the essential autophagy related 7 (ATG7) gene for mitophagy allows increased tolerance to starvation and prolonged lifespan of mice with lung cancer." (PMID 36614050, 2022). "In line, here, we showed that siRNAs against: ATG5, ATG7, or Beclin1 introduced to normoxic or hypoxic lung cancer cells prior to CIS treatment, did not changed their ability to induce senescence or senescence escaping." (PMID 35127467, 2021). "MAC and CoCl2 upregulated LC3‐II, Beclin1, ATG7, and BNIP3 in the different lung cancer cells." (PMID 30338933, 2018). "Again, AMPKa downstream proteins, mTOR and ATG7, were not changed, indicating that these two proteins may be not required for AMPKa in regulating autophagy in these lung cancer cells." (PMID 33312753, 2020).
lung carcinoma (continued). "Again, AMPKa downstream proteins, mTOR and ATG7, were not changed, indicating these two proteins may be not required for AMPKa regulation of autophagy in these lung cancer cells." (PMID 33312753, 2020). "Given the suppression of ATG7 by NASTRp, we further examined expression of ER stress markers, such as GRP78, CHOP, IRE1, PERK, ATF6 and XBP1, to determine whether NASTRp induces ER stress in lung cancer cells." (PMID 25897662, 2015). "Interestingly, knockout of Atg7 abolished LC3 processing but failed to prevent obatoclax induced death in lung cancer cells." (PMID 26585594, 2015). "Icotinib increased ATG3, ATG5, and ATG7 expression, but without affecting Beclin-1, VPS34 and ATBG14 levels in icotinib-resistant lung cancer cells." (PMID 35690866, 2022).
Obesity (52 papers, 2013 to 2025). Accumulation of substantial excess body fat. "The aim of this study was to analyze hepatic ATG7 mRNA and ATG7 protein expression regarding obesity-associated NAFLD." (PMID 36674839, 2023). "Severe hepatic downregulation of the autophagy gene Atg7 was found to occur in genetic and dietary models of obesity, and this caused insulin resistance through enhanced ER stress." (PMID 30116482, 2018). "Our findings that sedentary adult Atg7h&mKO mice became as obese and insulin resistant as control mice contrasts with a previous study, where skeletal muscle-specific loss of Atg7 was protective against obesity and insulin resistance." (PMID 28801668, 2017). "Conversely, partial Atg7 inhibition mitigated the decline in muscle mass associated with obesity." (PMID 41439967, 2025). "Finally, to deepen our understanding of ATG7 in NAFLD associated with obesity, we examined its relationships with the levels of several clinical parameters and metabolic and inflammatory mediators." (PMID 36674839, 2023). "We have reported that global Atg7-haploinsufficient mice showed compromised adaptation to metabolic stress and accelerated progression from obesity to diabetes, which was associated with aggravated liver steatosis and augmented inflammasome activation in adipose tissue." (PMID 35237600, 2022). "The apparently contradictory effects of obesity-associated downregulation of Atg7 and genetic knockout of Atg7 on hepatocyte insulin resistance may be better understood by considering that Atg7 knockout prevents obesity." (PMID 30116482, 2018). "Previous experiments demonstrated that Caspase-1 deficiency promotes adipogenesis through Atg7-mediated autophagy; we established an animal model by subjecting mice to a high-fat diet from week 8 until week 20 to investigate the impact of Caspase-1 deficiency under obesity conditions in vivo." (PMID 38672517, 2024). "Therefore, in the present study, we wanted to explore the role of ATG7 in NAFLD associated with obesity by studying the ATG7 mRNA and the protein expression of ATG7 in the liver of normal-weight subjects (the control group) and a cohort with MO and different degrees of liver involvement." (PMID 36674839, 2023). "Beyond the role of ATG7 in muscle homeostasis, adipose-specific deletion of Atg7 protects mice from obesity induced by a high-fat diet and reduces hepatic fat accumulation, inflammation, and fibrosis compared to wild-type control animals." (PMID 41439967, 2025). "First, an obesity-induced increase in the calcium-dependent protease calpain 2 leads to decreased Atg7 expression, followed by defective autophagy." (PMID 39683397, 2024). "The liver-specific overexpression of Atg7 or TFEB has also been shown to ameliorate obesity-related ER stress and insulin resistance, confirming the protective role of autophagy in this organ." (PMID 39683397, 2024). "Atg7 is vital for autophagy induction, it drives the initial phagophore formation; Obesity prevented CR-induced increase in Atg7 suggesting obesity interferes with all aspects of autophagy, making induction more difficult, while enhancing other aspects." (PMID 38166559, 2024). "Interestingly, in obesity models, such as high-fat-diet-fed mice and the leptin-deficient ob/ob mice, it has been reported that chronic overnutrition decreases hepatic ATG7 levels and autophagy activity, being liver-specific ATG7 overexpression sufficient to prevent hepatic steatosis." (PMID 38978979, 2024). "In contrast, many authors have stated that several autophagic genes, including ATG7, are upregulated in adipocytes from subjects with obesity." (PMID 36674839, 2023). "Adipose-specific deletion of autophagy-related 7 (Atg7) prevented high-fat diet (HFD)-induced obesity and improved insulin sensitivity in mice." (PMID 36642732, 2023).
Obesity (continued). "Somewhat unexpectedly, deletion of the autophagy-related gene-7 (ATG-7, specific to skeletal muscle) in mice conferred protection from diet-induced obesity and IR and was accompanied by increased fat oxidation and adipocyte browning." (PMID 37367914, 2023). "Hepatic Atg7 deletion in mice can also protect against the HFD-induced hepatic accumulation of lipids, insulin resistance, and associated obesity." (PMID 35982710, 2022). "These phenotypes were consistent with those of adipocyte‐specific Atg7 KO mice, where loss of autophagic function decreases WAT mass, enhances insulin sensitivity and protects the mice from HFD‐induced obesity." (PMID 35184387, 2022). "The downregulation of autophagy was observed, particularly in autophagy-related 7 (Atg7) expression levels in both genetic and dietary models of obesity, and in vivo and in vitro suppression of Atg7 led to impaired insulin signaling." (PMID 35392577, 2021). "The observed resistance to HFD-induced obesity and insulin resistance were associated with induction of FGF21, mirroring what was observed in muscle-specific Atg7 knockout mice, as discussed in the previous section." (PMID 34336862, 2021). "Ablation of autophagy-related protein 7 (Atg7) in the hypothalamus shows increased food intake and body weight, obesity and leptin resistance." (PMID 33849593, 2021). "The expression of Atg7 in adipose tissue has a protective effect on insulin sensitivity in high-fat diet induced obesity, indicating autophagy activation contributes to the regulation of fat mass." (PMID 32660483, 2020). "Mice with Atg7 deletion in skeletal muscle had reduced fat mass and were protected against both diet-induced insulin resistance and obesity." (PMID 32015340, 2020). "For instance, skeletal muscle-specific Atg7 KO mice are resistant to diet-induced obesity, which are accompanied by induction of WAT browning." (PMID 31590292, 2019). "Mice with adipocyte-specific inhibition of autophagy by ablation of autophagy-related gene 7 (Atg7) are resistant to diet-induced obesity and they exhibit improved insulin sensitivity, which is accompanied by the reduction of WAT mass but expansion of BAT." (PMID 31590292, 2019). "For instance, the specific deletion of Atg7 in murine hypothalamic neurons leads to hyperphagia and obesity, indicating that autophagy plays a crucial role in leptin hunger hormone sensitivity." (PMID 30249977, 2018). "Paradoxically, muscle- or liver-specific knockout of the Atg7 gene protected mice from obesity and insulin resistance by upregulating the expression of fibroblast growth factor (FGF21)." (PMID 30116482, 2018). "The role of autophagy in WAT inflammation has been examined in an ATG7-knock out mouse model, with beneficial effects on adipose tissue differentiation program in obesity." (PMID 29695642, 2018). "Using genetic and dietary models of obesity, a severe downregulation of autophagy was observed, particularly the expression level of Atg7 in the liver." (PMID 30249977, 2018). "Autophagy in hepatocytes is inhibited in obesity, and the dampened autophagy is mediated by down-regulated expression of Atg7, an autophagy-related protein." (PMID 28452943, 2017). "Recently, Yang and colleagues demonstrated that an obesity-induced increase in calcium-dependent protease calpain 2 activity led to degradation of Atg7 then to a defective autophagy." (PMID 27852058, 2016). "Recent findings established the relationship between insulin resistance in obesity and the decreased autophagy activity in liver, and restoration of Atg7 was shown to enhance the systemic glucose tolerance in mice." (PMID 23762877, 2013). "Interestingly, the expression of the E1-like protein ATG7 is elevated in the gastrocnemius muscles of obese individuals and murine models of obesity." (PMID 41439967, 2025). "In addition, HFD-fed Atg7 knockout mice presented decreased expression of hepatic lipogenic genes and were protected against diet-induced obesity and insulin resistance." (PMID 36674839, 2023).
Obesity (continued). "However, contrasting findings were observed in liver-specific Atg7 knockout mice, which displayed protection from diet-induced obesity and insulin resistance, although this study did not examine insulin signaling in the liver." (PMID 34336862, 2021). "Interestingly the increased expression of Atg7 in the heart prevents the heart from hypertrophying in response to high-fat diet-induced obesity." (PMID 32848832, 2020). "Atg7 gene deletion specifically in mice adipose tissue made them resistant to diet-induced obesity." (PMID 32015340, 2020). "Interestingly, similar observation has been described in adipocyte-specific autophagy related 7 knock out (ATG7 KO) model in the context of diet-induced obesity study." (PMID 29695642, 2018). "Moreover, a severe downregulation of Atg7 expression in the liver was observed in both genetic and dietary models of obesity." (PMID 30249977, 2018). "Atg-7 knockout mice are insulin-sensitive and resistant to the development of obesity." (PMID 29507613, 2018). "In addition, knockdown of autophagy genes Atg5 and Atg7 in adipocytes can improve insulin sensitivity and relieve obesity." (PMID 27843198, 2016). "Moreover, direct genetic evidence was obtained that ATG7 participates in normal development and metabolic modulation in POMC neurons, indicating potential roles of Atg7 deficiency in the pathogenesis of obesity and aging-related metabolic syndrome." (PMID 26404030, 2015). "In accordance with results from studies in human obesity, we found an increase of Atg5 and Atg7 expression in visceral adipose tissue of WOKW rats, suggesting parallel alterations in the endocrine function of adipose tissue both in human and in WOKW metabolic syndrome." (PMID 23668414, 2013). "One of the supporting studies is that the inhibition of autophagy using small interfering RNA targeted to Atg7 increases proinflammatory gene expression (i.e., IL-1β, IL-6, and IL-8) in adipose tissue, thus suggesting that autophagy acts to suppress inflammation that is excessive during obesity." (PMID 41194853, 2025). "Furthermore, during obesity progression, the abundance of ATG7 in the liver increases, which may correlate with elevated serum glucose, insulin, and FFA levels." (PMID 41439967, 2025). "Likewise, the deletion of autophagy-related ATG5 or ATG7 in hypothalamic POMC neurons is found to trigger abnormal glycolipid metabolism and severe obesity in the ATG5-or ATG7-deficient mice, suggesting the involvement of ER-phagy in the degradation of misfolded POMC." (PMID 37152279, 2023). "Targeted deletion of the Atg7 gene in adipose tissue can destroy autophagy pathway, which protects mice from high-fat diet-induced obesity and insulin resistance, suggesting that activation of the autophagy-mediated pathway may be one of the mechanisms of obesity-induced insulin resistance." (PMID 32660483, 2020). "Adipocyte specific ATG7 k/o mice are lean with reduced fat mass, increased insulin sensitivity, an increase in BAT thermogenesis and are resistant to diet-induced obesity." (PMID 32265830, 2020). "On the contrary, knock down of Atg7 in the mediobasal hypothalamus as well as in propriomelanocortin (POMC) neurons, favors the onset of an obesity phenotype and leptin resistance." (PMID 24376631, 2013). "For our first finding, the hepatic expression of ATG7 was not different depending on the presence of obesity." (PMID 36674839, 2023). "As shown in our data, the mRNA levels of autophagic genes (Atg5, Atg7, Beclin1, and Tfeb) were found to be remarkably increased in the HFD + DSS group compared with the HFD group, suggesting that uptake of fatty acids triggers autophagy in obesity-related colitis." (PMID 34451919, 2021). "The exact mechanism for the downregulation of Atg7 was not revealed in these studies; however, it is known that proteinopathy and obesity are characterized by increased mammalian (mechanistic) target of rapamycin complex 1 (mTORC1) activity, which suppresses Atg7 expression." (PMID 32848832, 2020).
Obesity (continued). "It appeared that the macrophage-specific deletion of the Atg7 gene did not affect obesity." (PMID 27229537, 2016). "Hence, ATG7-mediated autophagy seems to be influenced by liver involvement and not by obesity." (PMID 36674839, 2023).